TWNK (twinkle mtDNA helicase)
Description:
[Isoform 1]: Mitochondrial helicase involved in mtDNA replication and repair. Might have a role in mtDNA repair. Has DNA strand separation activity needed to form a processive replication fork for leading strand synthesis which is catalyzed by the formation of a replisome complex with POLG and mtSDB. Preferentially unwinds DNA substrates with pre-existing 5'-and 3'-single-stranded tails but is also active on a 5'-flap substrate. Can dissociate the invading strand of immobile or mobile D-loop DNA structures irrespective of the single strand polarity of the third strand. In addition to its DNA strand separation activity, also has DNA strand annealing, DNA strand-exchange and DNA branch migration activities. [Isoform 2]: Lack DNA unwinding and ATP hydrolysis activities. Does not bind single-stranded or double-stranded DNA.
Synonyms: C10orf2; PEO1; PEO; TWINKLE; FLJ21832; TWINL; ATXN8; IOSCA; MTDPS7; PEOA3; PRLTS5; SANDO; SCA8
Tractability: Antibody: UniProt places it where antibodies can reach, with high confidence. PROTAC: ubiquitination databases record sites on it.
Gene: Protein-coding gene on chromosome 10 (100,987,367 to 100,994,403, forward strand). Ensembl gene ENSG00000107815.
Subcellular location: Mitochondrion matrix, mitochondrion nucleoid; Mitochondrion inner membrane
Pathways (Reactome):
DNA Replication: Strand-asynchronous mitochondrial DNA replication
Metabolism of proteins: Mitochondrial protein degradation
Organelle biogenesis and maintenance: Transcriptional activation of mitochondrial biogenesis
Gene Ontology:
Molecular function: 5'-3' DNA helicase activity; ATP hydrolysis activity; identical protein binding; lipid binding; protease binding; protein binding; single-stranded DNA binding; ATP binding; DNA helicase activity
Biological process: DNA-templated DNA replication; mitochondrial DNA replication; mitochondrial transcription; protein hexamerization; DNA replication
Cellular component: mitochondrial chromosome; mitochondrial nucleoid; mitochondrion; mitochondrial inner membrane; mitochondrial matrix
Genetic constraint (gnomAD): Loss-of-function variants: 36 observed, 62.58 expected, observed/expected ratio (o/e) 0.58, 90% interval 0.44 to 0.76. The upper end of that interval is the gene's LOEUF score, 0.76, which puts it in group 3 of 6, group 1 being the genes least tolerant of losing a copy. Missense variants: 714 observed, 930.33 expected, observed/expected ratio (o/e) 0.77, 90% interval 0.72 to 0.82. Synonymous variants: 349 observed, 368.98 expected, observed/expected ratio (o/e) 0.95, 90% interval 0.87 to 1.03.
Gene-disease validity (ClinGen):
ClinGen rates the evidence that TWNK causes each of these diseases.
Perrault syndrome 5 (autosomal recessive): Definitive.
Homologues: Orthologues: macaque TWNK (97% identical), pig TWNK (89% identical), dog TWNK (88% identical), rabbit TWNK (88% identical), mouse Twnk (87% identical), rat Twnk (86% identical), guinea pig TWNK (86% identical), chimpanzee TWNK (84% identical), zebrafish twnk (60% identical), tropical clawed frog twnk (60% identical), Drosophila melanogaster mtDNA-helicase (36% identical), Caenorhabditis elegans twnk-1 (26% identical).
Diseases named in the same sentence as TWNK in open-access papers:
TWNK is named in the same sentence as 60 diseases in open-access papers, as found by Europe PMC text mining. Sharing a sentence is not in itself a finding about the gene and the disease. The quoted sentences say what the papers report.
Perrault syndrome (14 papers, 2017 to 2025). Perrault syndrome (PS) is characterized by the association of ovarian dysgenesis in females with sensorineural hearing impairment. "In this study, a total of seven TWNK variants were identified, five of which were newly reported in connection with Perrault syndrome caused by TWNK gene mutations." (PMID 39780253, 2025). "The role of mtDNA in Perrault syndrome’s pathogenesis is substantiated by causal mutations in the mitochondrial DNA/RNA helicase TWNK/PEO1 and in the mitochondrial transcription factor TFAM." (PMID 38927630, 2024). "WES revealed a compound heterozygous state with two variants in the TWNK gene and a diagnosis of Perrault Syndrome was made." (PMID 37932750, 2023). "Here we aim to report the detailed phenotypic (clinical, laboratory, imaging and neuropathological) characteristics and the genetic data of our case with Perrault syndrome caused by TWNK mutations." (PMID 31852434, 2019). "Studies on genotype–phenotype correlation from the hitherto reported cases indicate that patients with Perrault syndrome caused by TWNK mutations will manifest neurological signs in adulthood." (PMID 31455392, 2019). "This study demonstrates that TWNK associated Perrault syndrome has a much broader phenotype as originally published." (PMID 31852434, 2019). "Studies on genotype–phenotype correlation from the hitherto reported cases indicate that all patients with Perrault syndrome caused by TWNK mutations will manifest neurological signs in adulthood." (PMID 31455392, 2019). "The TWNK gene is coding the mitochondrial protein Twinkle and currently there are only two reports characterizing the phenotype of TWNK-associated Perrault syndrome." (PMID 31852434, 2019). "TWNK is also believed to cause Perrault syndrome when harbouring deleterious variants." (PMID 37148394, 2023). "Moreover, mutations in the TWNK gene were described in Perrault syndrome, a very rare autosomal recessive disease presenting with sensorineural hearing loss, ataxia, and ovarian dysfunction." (PMID 33396418, 2020). "Here we report a Spanish familial case of Perrault syndrome with neurological manifestations and show it is caused by two compound heterozygous mutations in the TWNK gene, one of which is novel whereas the other was previously reported in a case of hepatocerebral syndrome." (PMID 31455392, 2019). "In 2014, a new phenotype Perrault syndrome was associated to TWNK gene alterations." (PMID 31852434, 2019). "In HSD17B4-dependent Perrault syndrome and in TWNK-dependent Perrault syndrome, cerebellar atrophy was only described besides non-specific findings." (PMID 31852434, 2019). "The genetic study included genotyping and haplotype analysis for microsatellite markers close to the genes involved in Perrault syndrome, whole-exome sequencing, and Sanger sequencing of the coding region of the TWNK gene." (PMID 31455392, 2019). "Pathogenic/likely pathogenic variants in HARS2, CLPP, LARS2, TWNK, ERAL1, and PROPR may cause Perrault syndrome-related OD." (PMID 38812815, 2024). "The dominant TWNK variants cause progressive external ophthalmoplegia with mitochondrial DNA deletions, autosomal dominant 3 (PEOA3), while the recessive variants cause mitochondrial DNA depletion syndrome 7 (MTDPS7) and Perrault syndrome 5 (PRLTS5)." (PMID 32234020, 2020).
Ataxia (11 papers, 2008 to 2025). Ataxia refers to impaired coordination of voluntary muscle movement. "All reported cases due to TWNK variants have included neurologic features, such as ataxia and axonal sensorimotor neuropathy." (PMID 37932750, 2023). "We determined that the TWNK variant was causative, as it has been reported that TWNK variants cause cerebellar ataxia, sensorineural deafness, and sensory neuropathy, which our patient presented." (PMID 32234020, 2020). "Screening for TWNK variants should be considered in cases of cerebellar ataxia associated with deafness and/or peripheral neuropathy, even if the onset is not early." (PMID 32234020, 2020). "Other variants in TWNK induce a recessive syndrome found in the Finnish ethnic group that produces infantile onset spinocerebellar ataxia, with mtDNA depletion found in the liver and brain." (PMID 33426505, 2020). "The founder variant in the TWNK gene has been identified in the genetically isolated population of Finland only, where IOSCA is the second-most common inherited ataxia." (PMID 36004034, 2022). "Six of these candidate variants were located in genes related to ataxia phenotype including ATM, GALC, SPTBN2, SYNE1, and TWNK." (PMID 31455392, 2019). "The coexistence of severe hypoacusis, spastic limb weakness, ataxia, polyneuropathy, gonadal dysgensia, hyperintense signals in the cerebellum and the presence of the mtDNA multiple deletion could indicate the impairment of the TWNK gene." (PMID 31852434, 2019).
infantile-onset spinocerebellar ataxia (9 papers, 2016 to 2023). "Apart from PEO, mutations in the TWNK gene have been discovered in a variety of mitochondrial illnesses, including mtDNA depletion syndromes (MDSs), Perrault syndrome, infantile-onset spinocerebellar ataxia (IOSCA), and other ataxia neuropathies." (PMID 36157077, 2022). "In fact, TWNK mutations also cause mtDNA depletion, associated with more severe phenotypes, such as infantile onset spinocerebellar ataxia (IOSCA), or other phenotypic variants associated with mtDNA multiple deletions such as Perrault syndrome." (PMID 34208592, 2021). "Mutations of TWNK are well-described in mitochondrial DNA depletion syndrome 7 (MTDPS7) which is also known as infantile-onset spinocerebellar ataxia (infantile onset-SCA) and autosomal dominant progressive external ophthalmoplegia 3 (autosomal dominant-PEO3)." (PMID 31852434, 2019). "One heterozygous likely pathogenic variant c.1003 C>A and another variant of unknown significance c.2050 A>C in the TWNK gene causing mitochondrial DNA depletion syndrome 7 or infantile-onset spinocerebellar ataxia (IOSCA) were detected." (PMID 36004034, 2022).
autosomal dominant progressive external ophthalmoplegia (5 papers, 2017 to 2025). Autosomal dominant form of progressive external ophthalmoplegia. "TWNK variants have been associated with different pathological phenotypes, including autosomal dominant progressive external ophthalmoplegia (adPEO), whereas some patients also presented late onset parkinsonism." (PMID 40362688, 2025). "The exceptions were the two cases of autosomal dominant progressive external ophthalmoplegia due to a pathogenic variant in the TWNK gene, presenting at 50 and 72 years old." (PMID 36859275, 2023). "Pathogenic role of heterozygous TWNK mutations have been first discovered in families with autosomal dominant progressive external ophthalmoplegia (PEOA3; OMIM #609286)." (PMID 28178980, 2017). "In addition, clinicians should keep in mind that there are mitochondrial syndromes and phenotypes resulting from nDNA pathogenic variants, such as variants in the POLG and TWNK genes responsible for Alpers syndrome and Autosomal Dominant Progressive External Ophthalmoplegia, respectively." (PMID 36859275, 2023). "Also, different mutations in TWNK have been reported in autosomal dominant progressive external ophthalmoplegia (AdPEO, MIM 609286) and in three autosomal recessive disorders." (PMID 31455392, 2019).
progressive external ophthalmoplegia (5 papers, 2008 to 2021). A mitochondrial myopathy characterized by slowly progressive paralysis of the levator palpebrae, orbicularis oculi, and extraocular muscles. "Autosomal dominant mutations in the TWNK gene, which encodes a mitochondrial DNA helicase, cause adult-onset progressive external ophthalmoplegia (PEO) and PEO-plus presentations." (PMID 35011763, 2021).
deafness (3 papers, 2020 to 2025). An inherited or acquired condition characterized by the complete loss of the ability to hear from one or both ears. "In contrast, patients with TWNK mutations showed a wide range of hearing levels, from mild impairment to complete deafness." (PMID 39780253, 2025).
mitochondrial neurogastrointestinal encephalomyopathy (3 papers, 2008 to 2022). A syndrome characterized by the association of gastrointestinal dysmotility, peripheral neuropathy, chronic progressive external ophthalmoplegia and leukoencephalopathy. "Hypergonadotrophic hypogonadism has been reported in the context of mitochondrial neurogastrointestinal encephalopathy (MNGIE) and/or infantile onset spinocerebellar ataxia caused by recessive variants in the TWNK gene, which encodes for mtDNA helicase Twinkle." (PMID 35552684, 2022).
optic atrophy (3 papers, 2017 to 2023). A disorder characterized by loss of optic nerve fibers. "Neurological symptoms due to myopathy and peripheral neuropathy were frequently investigated and treated in patients with OPA1 and TWNK mutations despite their features of optic atrophy, ptosis and ophthalmoplegia constituting the predominant phenotype." (PMID 37246228, 2023). "A two-year-old girl with motor delay and optic atrophy, with TMS negative, underwent molecular testing and was found to have compound heterozygous variants in the TWNK gene." (PMID 36004034, 2022).
acute liver failure (2 papers, 2018 to 2022). Rapid deterioration of liver function causing encephalopathy and coagulopathy. "Apparently, pathogenic mutations in the nuclear genes POLG, TWNK and WARS2, and in the mitochondrial genes tRNALeu and tRNALys, all affecting intramitochondrial transcription and/or translation, have been associated with valproate-induced acute liver failure." (PMID 29783990, 2018).
cardiomyopathy (2 papers, 2019 to 2025). A disease of the heart muscle or myocardium proper. "Mutations in the gene TWNK (or PEO) encoding the helicase Twinkle have been widely reported in families with autosomal dominant PEO plus cardiomyopathy." (PMID 31718067, 2019).
Dystonia (2 papers, 2025). An abnormally increased muscular tone that causes fixed abnormal postures. "Progressive dystonia was associated with ANO3 and a microdeletion in Xp11.4 including the CASK gene, whereas progressive athetosis was seen with ATM and TWNK." (PMID 40326640, 2025).
Hearing impairment (2 papers, 2012 to 2022). A decreased magnitude of the sensory perception of sound. "Although the role of TWNK gene in hearing impairment is clear and accordingly reflected in published literature as well as in the present article, for the presented gene variants, a correlation to hearing problems could not yet be established and requires more scientific data." (PMID 36143929, 2022).
liver failure (2 papers, 2014 to 2024). A liver disease characterized by the liver losing or has lost all of its function. "Differential diagnosis should also be considered with other mitochondrial disorders causing liver failure (MPV17, POLG1, POLG2, TFAM, TWNK, TRMU)." (PMID 38756539, 2024).
Mitochondrial myopathy (2 papers, 2024 to 2025). "In conclusion, while TWNK mutations are strongly associated with mitochondrial myopathy and PEO, their phenotypic expression is modulated by a complex interplay of genetic and non-genetic factors." (PMID 41008644, 2025).
ovarian dysgenesis (2 papers, 2017 to 2025). "Previous studies showed that patients with TWNK gene mutations primarily exhibit hearing loss and high arched feet, while female patients often experience ovarian dysgenesis and other gonadal dysfunctions." (PMID 39780253, 2025).
Parkinsonism (2 papers, 2021 to 2022). Characteristic neurologic anomaly resulting from degeneration of dopamine-generating cells in the substantia nigra, a region of the midbrain, characterized clinically by shaking, rigidity, slowness of movement and difficulty with walking and gait. "Remarkably, variants in POLG, TWNK, and TFAM are not only known as a monogenic cause of primary mitochondrial disorders (occasionally presenting with parkinsonism) but can also increase the risk for PD." (PMID 34828446, 2021).
E. coli infection (1 paper, 2022). "Here, the expression of nuclear genes POLG, SSBP1, TWNK, and TOP1 during E. coli infection was consistent with that of mtDNA." (PMID 36430657, 2022).
neuropathy (1 paper, 2025). A disorder affecting the nervous system that manifests with pain, tingling, numbness, and/or muscle weakness. "Intriguingly, all except one patient (harboring a TWNK mutation) showing neuropathy were part of cluster 2 (Fisher’s Exact test, p = 0.0027∗∗)." (PMID 39801833, 2025).
oculopharyngeal muscular dystrophy (1 paper, 2021). Oculopharyngeal muscular dystrophy (OPMD) is an adult-onset progressive myopathy characterized by progressive eyelid ptosis, dysphagia, dysarthria and proximal limb weakness. "Another frequently considered alternative diagnosis before confirmation of TWNK mutations was oculopharyngeal muscular dystrophy (OPMD) in five patients (20%)." (PMID 35011763, 2021).
prostate carcinoma (1 paper, 2023). A carcinoma that arises from epithelial cells of the prostate gland. "Furthermore, a number of mtDNA replication–related genes are upregulated in human prostate cancer, and TWNK levels correlate with MYC mRNA." (PMID 37971875, 2023).
mitochondrial disease (9 papers, 2015 to 2025). "PEO is a mitochondrial disease caused by either mutations, rearrangements, or deletions in mitochondrial DNA (mtDNA), or mutations in nuclear genes that participate in the maintenance of mtDNA (e.g., POLG, TWNK)." (PMID 41149856, 2025). "Interestingly, mutations in TWNK, ATAD3A, and VPS35 are linked to several severe mitochondrial diseases having in common mtDNA instability, therefore representing a cluster of proteins involved in specific mtDNA turnover." (PMID 36344526, 2022).
tumour (3 papers, 2018 to 2025). "The mtDNA replication factors POLG2, TOP1 MT and TWNK were also found to be down-regulated in the GBM50 and GBM3 tumours." (PMID 30208958, 2018).
infection (2 papers, 2022 to 2025). The state of being infected such as from the introduction of a foreign agent such as serum, vaccine, antigenic substance or organism. "We noted that infection also induced the expression of the mtDNA transcription factor TFAM and mtDNA helicase TWNK, whose mild overexpression increases mtDNA levels by ~1.5x-fold, comparable to changes we observed during infection." (PMID 40811546, 2025). "Contrary to our expectation, the loss of ATF4 did not block the increase in TFAM and TWNK transcripts during infection." (PMID 40811546, 2025). "Because infection induced the expression of TFAM and TWNK, we posited that ATF4 regulated mtDNA levels in a TFAM- and TWNK-dependent manner." (PMID 40811546, 2025). "We posited that the increase in mtDNA was regulated by an infection-induced transcription factor upstream of TFAM and TWNK." (PMID 40811546, 2025). "Infection with E. coli increased expression of polymerase gamma (POLG), single-stranded DNA-binding protein (SSBP1), TWINKLE (TWNK), and DNA topoisomerase 1 (TOP1) genes." (PMID 36430657, 2022).
autosomal dominant disease (1 paper, 2025). Autosomal dominant form of disease. "Notably, to date, no nonsense heterozygous TWNK variants have been reported in association with autosomal dominant disease." (PMID 41008644, 2025). "However, because heterozygous TWNK null variants have not been identified as a known mechanism of pathogenicity consistent with autosomal dominant disease, the PVS1 criterion should not be applied in this specific clinical context." (PMID 41008644, 2025).
TWNK also shares sentences with these, for which no sentence is quoted: mitochondrial DNA depletion syndrome (7 papers); cancer (5); peripheral neuropathy (4); ptosis (3); genetic disease (2); Infantile onset (2); ovarian dysfunction (2); Perrault syndrome 5 (2); Spastic paraplegia (2); Alpers syndrome (1); Athetosis (1); cerebellar ataxia (1); Cerebral atrophy (1); Encephalopathy (1); endometriosis (1); epilepsy (1); frontotemporal dementia (1); Hypergonadotrophic hypogonadism (1); Hypoglycemia (1); infertile (1); Intellectual disability (1); mitochondrial DNA depletion syndrome 9 (1); mitochondrial recessive ataxia syndrome (1); movement disorder (1); myopathy (1); neurological disease (1); ophthalmoplegia (1); optic atrophy type 1 (1); ovarian adenocarcinoma (1); ovarian carcinoma (1).
A further 6 diseases each share a sentence with TWNK in 1 paper.